MIF (macrophage migration inhibitory factor)
Diseases named in the same sentence as MIF in open-access papers (continued):
Sharing a sentence is not in itself a finding about the gene and the disease.
autoimmune disease (continued). "As is ubiquitously expressed by a variety of cell types of multiple tissues, MIF participates in the pathogenesis of many inflammatory and autoimmune diseases by overriding the immunosuppressive effects of glucocorticoids." (PMID 35624475, 2022). "As a proinflammatory mediator secreted by numerous immune cells, MIF promotes inflammation and autoimmune diseases mainly by binding with the receptor CD74 and co-receptor CD44, CXCR4, or CXCR2." (PMID 36046240, 2022). "Recent studies have identified MIF as a pro-inflammatory cytokine that plays an essential role in inflammatory and autoimmune diseases." (PMID 36225941, 2022). "Prior publications reported a pivotal role of MIF in the pathogenesis of type 2–mediated inflammation, especially in allergic and autoimmune diseases." (PMID 34305594, 2021). "Consistent with our findings, they reported a significant lower level of MIF protein in OA patients than in AS and RA patients, suggesting a different role of MIF between OA and autoimmune diseases." (PMID 33610191, 2021). "In a similar manner, MIF seems to play a pathogenetic role in immune-inflammatory and autoimmune diseases of the skin, including psoriasis, atopic dermatitis, eczema and UV radiation damage." (PMID 33401503, 2021). "Accumulating evidence showed that MIF exhibited a variety of biological functions in the inflammation and immune response, and was closely involved in allergic and autoimmune diseases." (PMID 34305594, 2021). "Macrophage migration inhibitory factor (MIF) is a potent and pleiotropic cytokine secreted by activated T cells and macrophages that plays a critical role in inflammatory and autoimmune diseases." (PMID 34445689, 2021). "MIF was the first cytokine to be considered an important mediator of chronic inflammatory and autoimmune diseases, mediating the generation of inflammatory cells." (PMID 32560699, 2020). "One of the “bad” players in viral and autoimmune diseases is the macrophage migration inhibitory factor (MIF), a pleiotropic proinflammatory cytokine that mediates diverse immune responses." (PMID 33584306, 2020). "The circulating levels of MIF are elevated in T2D, Type 1 Diabetes and a number of other autoimmune diseases." (PMID 33101053, 2020). "Although MIF has been primarily studied for its role in the pathogenesis of autoimmune diseases, it has also been shown to promote tumorigenesis and it is over expressed in various malignant tumors." (PMID 29707160, 2018). "MIF has originally attracted much attention as a central mediator of several immunoinflammatory and autoimmune diseases." (PMID 29707160, 2018). "MIF is the constituent component of constituting inflammatory and it is the pathogenesis of autoimmune diseases." (PMID 29312536, 2017). "In accordance with what had been found in the patients with other autoimmune diseases, we also demonstrated increased MIF mRNA levels of PBMCs in HT patients." (PMID 25861163, 2015). "It has long been known that the secretion of MIF is correlated to infectious diseases, autoimmune diseases, heart and vascular diseases, and cancer." (PMID 25821355, 2015). "The use of anti-MIF neutralizing antibodies has be shown to be therapeutically efficacious in several models of inflammatory and autoimmune diseases." (PMID 26617609, 2015). "Macrophage migration inhibitory factor (MIF) is commonly recognized as playing vital roles in various autoimmune diseases." (PMID 25506398, 2014). "Because MIF was also highly expressed in patients with autoimmune diseases and inflammation, those patients were excluded from the current study." (PMID 22952837, 2012). "Macrophage Migration Inhibitory Factor (MIF) is a key mediator of inflammatory responses and innate immunity and has been implicated in the pathogenesis of several inflammatory and autoimmune diseases." (PMID 23028743, 2012). "A sizeable body of work has emerged over the past 5 years elucidating the role of MIF in the pathogenesis of autoimmune disease including RA." (PMID 20596538, 2010).
autoimmune disease (continued). "Serum levels of MIF have been shown to be correlated with the disease activity in several autoimmune disorders including juvenile idiopathic arthritis, rheumatoid arthritis and Wegener's granulomatosis." (PMID 17470266, 2007). "There is increasing evidence for a role of MIF as a proinflammatory cytokine in autoimmune diseases." (PMID 17470266, 2007). "By counter-regulating the immunosuppressive effects of glucocorticoids, MIF might also contribute to the development of steroid resistance in conditions such as asthma and autoimmune diseases." (PMID 41159021, 2025). "However, in chronic inflammatory conditions, sustained MIF expression can contribute to pathological inflammation, leading to tissue damage and autoimmune diseases." (PMID 41159021, 2025). "Besides their importance in normal and malignant cell settings, MIF and CD74 are implicated in the etiology of numerous autoimmune diseases, including autoimmune liver disease, kidney disease, and multiple sclerosis." (PMID 38730725, 2024). "Modulating WISP1 and/or MIF activity could provide new strategies to treat conditions such as autoimmune diseases, chronic inflammatory conditions such as asthma and COPD, and even cancer." (PMID 39337534, 2024). "Macrophage migration inhibitory factor (MIF) is a pleiotropic cytokine involved in many autoimmune diseases and chronic inflammatory disorders as a modulator of responses of immune populations and a prominent function in cell survival signaling beyond its proinflammatory function." (PMID 37674165, 2023). "In a mouse model of experimental ischaemia-reperfusion injury, renal tubular injury was more severe in MIF, MIF-2 and CD74 knockout mice than in wild-type control mice, and the autoimmune disease systemic lupus erythematosus (SLE) can cause renal inflammation known as lupus nephritis." (PMID 36445632, 2023). "Furthermore, MIF-targeted treatments are being examined in preclinical studies or early-stage clinical trials due to their specific functions observed in different autoimmune diseases." (PMID 34535196, 2021). "In addition, MIF was reported to have a critical role in various autoimmune diseases, such as multiple sclerosis (MS), rheumatic arthritis (RA) and autoimmune hepatitis." (PMID 34662363, 2021). "It has been a new hot spot about the relationship between MIF-173G/C and autoimmune diseases." (PMID 32410863, 2020). "Recent studies have been conducted to investigate the association between macrophage migration inhibitory factor- (MIF-) 173G/C gene polymorphism and autoimmune diseases; however, the results were not exactly identical." (PMID 32410863, 2020). "There was no significant heterogeneity between the MIF-173G/C polymorphism and autoimmune diseases (both P > 0.1), so the fixed effects model was used for meta-analysis." (PMID 32410863, 2020). "In the current study, to focus on evaluating the relationship between MIF and cardiac function impairment in STEMI patients, we excluded patients with autoimmune diseases, which may affect MIF concentrations dramatically." (PMID 30983881, 2019). "Additionally, macrophage migration inhibitory factor (MIF) is thought to play an important role in the pathogenesis of autoimmune diseases, especially in both rodent and human IBD." (PMID 31284478, 2019). "High levels of MIF are indicative of autoimmune diseases and severe inflammatory states." (PMID 31632367, 2019). "Also more insights into the effects of autocrine and T helper cell‐derived MIF on their development will lead to better understanding of the role of B cells as central players in MS and other autoimmune diseases." (PMID 30160778, 2018). "Along with other novel approaches, the pharmacologic targeting of MIF either by monoclonal antibodies or by small molecule antagonists for the treatment of autoimmune diseases has attracted considerable interest and new generation inhibitors are actively investigated." (PMID 29095944, 2017).
autoimmune disease (continued). "Finally, studies from Arab countries are scarce with respect to MIF variations in any infectious or autoimmune diseases, making ethnic comparisons difficult and only permitting comparisons with results from non-Arab populations." (PMID 27014277, 2016). "Associations between MIF −173*C and −794 CATT5−8 polymorphisms and autoimmune disease." (PMID 26617609, 2015). "Also, high serum levels of MIF were reported in other autoimmune diseases such as SLE and type 1 diabetes mellitus." (PMID 25506398, 2014). "MIF is an important cytokine in a variety of autoimmune diseases and in particular SLE." (PMID 23968496, 2013). "By multivariable analyses, IL-8 and TNFα, but not MIF levels, were associated with the diagnosis of an underlying autoimmune disease." (PMID 20596538, 2010). "MIF is known to induce the expression of key proinflammatory genes, including IL-1, TNF, IL-6, IL-8, COX-2, and MMPs, and has been implicated in the development of many acute inflammatory and autoimmune diseases as well as chronic inflammatory metabolic disorders." (PMID 34445689, 2021). "For the frequencies of ‐794 CATT5‐8, MIF polymorphism was similar to other studies that evaluated autoimmune diseases in patients from western Mexico, but there is no existing report that determines the distribution of this polymorphism in cancer from this population." (PMID 31978276, 2020). "Interestingly, resistance to both endogenous and exogenous glucocorticoids is primarily induced by the pro-inflammatory cytokine macrophage migration inhibitory factor (MIF) that plays a role in animal models of autoimmune disease, such as multiple sclerosis, Guillain-Barre syndrome, and SLE." (PMID 30287776, 2018). "In addition, MIF exhibits an endogenous counter-regulation of the anti-inflammatory effects of GCs and leads to a potentially decreased response to GC-treatment in autoimmune diseases." (PMID 30475854, 2018). "However, in autoimmune disease MIF concentrations can fluctuate to markedly higher levels." (PMID 26617609, 2015). "Eventually, targeting of MIF may offer therapeutic options in this autoimmune disease." (PMID 17470266, 2007). "MIF can regulate CD74 activity, leading to homeostatic imbalances such as inflammation, tumors, and autoimmune diseases." (PMID 40867844, 2025). "The well-documented involvement of MIF and CD74 in the balance of the immune system and the pathogenesis of autoimmune diseases suggests they are promising candidates for future research as biomarkers of irAE development following ICB treatment." (PMID 38730725, 2024). "Recently, therapeutics aimed at disrupting MIF and/or CD74 binding have been considered in the treatment of several autoimmune diseases." (PMID 38730725, 2024). "Therefore, MIF is recognized as a biomarker or pharmacological target for different diseases, and MIF inhibitors might have considerable therapeutic benefit for numerous inflammatory and autoimmune diseases." (PMID 38035087, 2023). "MIF and DDT have been suggested to play a key role in the pathogenesis of several autoimmune diseases, such as multiple sclerosis and type 1 diabetes, as well as in the development and progression of certain forms of cancers." (PMID 33401503, 2021). "Remarkably, MIF and PAI1 are expressed by DN T cells, together with RANTES, promoting a T-cell cytokine-enhancing effects that is involved in processes like autoimmune disease and aging, mediated by CD4+ and CD8+ T cells." (PMID 33383950, 2020). "MIF is an immunomodulatory factor that regulates chemotaxis and survival in neutrophils, and is involved in AAV and other autoimmune diseases." (PMID 31248381, 2019). "Previous studies have suggested similar roles for MIF and DDT, but the extent of crossover of these two molecules in autoimmune disease is unclear." (PMID 30546906, 2018).
autoimmune disease (continued). "Macrophage migration inhibitory factor (MIF) is a pro-inflammatory cytokine, which is required for antigen-driven T-cell activation and sustained inflammation in autoimmune disorders." (PMID 30475854, 2018). "MIF is a pro-inflammatory mediator and an upstream regulator of expression of many cytokines, including IL-1b, IL-8, IFN-ɤ, TNF-α, and IL-6 in autoimmune diseases." (PMID 25506398, 2014). "Macrophage migration inhibitory factor (MIF) is a primary immune response regulator that has a role in the development of serious diseases, such as acute respiratory distress syndrome (ARDS), asthma, cancer and autoimmune disorders." (PMID 33356032, 2021). "In addition, we compared serum MIF levels of SSc patients to SLE patients, as an autoimmune disease control group, and healthy controls." (PMID 30546906, 2018). "While polymorphisms in MIF have been associated with SLE in both Asian and non-Asian cohorts, differences in MIF levels or MIF genotype between ethnicities in patients with autoimmune disease have not been previously reported." (PMID 27453287, 2016). "Macrophage migration inhibitory factor (MIF) is a pro-inflammatory cytokine that regulates the innate immune response and has been shown to be important in various autoimmune diseases, in addition to being involved in cell proliferation, cell survival, migration and metastasis in cancer." (PMID 25289107, 2014). "Considering the relevance of MIF in patients suffering from autoimmune diseases such as SLE and RA, we are of the opinion that the presence of hapten-modified MIF in patients with ACD are worth exploring to investigate if haptenated MIF could be a general disease biomarker for the condition." (PMID 35465102, 2022). "Interactions between MIF, TLR4 and TCR/CD3 are complex and understanding their nature could have translational impacts on immunomodulatory approaches for treating inflammatory and autoimmune diseases." (PMID 31253838, 2019). "In addition to stabilizing and chaperoning MHC class II molecules to the cell surface, CD74 serves as the primary receptor for binding macrophage migration inhibitory factor (MIF), a pleiotropic pro-inflammatory protein involved in many inflammatory and autoimmune diseases." (PMID 26104759, 2015). "The induction and regulation of MIF in autoimmune diseases is not well characterized." (PMID 17470266, 2007). "Despite the MIF mRNA expression in cartilage was not correlated with the plasma MIF protein levels, we observed that both of them were reduced in OA patients, suggesting a protective role of MIF in OA which was different from what was reported in autoimmune disorders such as RA, AS, and SLE." (PMID 33610191, 2021). "Most studies of MIF genetics have revealed its predominant role in autoimmune disease severity or clinical manifestations rather than in disease susceptibility, and differences observed in disease predisposition may reflect different effect sizes in genetically distinct populations." (PMID 31701681, 2020). "However, unlike the case in cancer and autoimmune diseases, MIF may have a protective effect in the heart during ischemia or other cardiovascular diseases." (PMID 25821355, 2015).
melanoma (87 papers, 2009 to 2026). A malignant, usually aggressive tumor composed of atypical, neoplastic melanocytes. "We also correlated functional variant MIF alleles with melanoma incidence and progression in patients." (PMID 41122966, 2025). "Additional in vivo studies have linked MIF with angiogenesis in melanoma, where anti-MIF antibodies in mice reduced angiogenesis." (PMID 41159021, 2025). "Findings from our survival analysis are consistent with existing literature demonstrating that increased MIF levels are associated with worse prognosis in patients with melanoma; particularly in patients with advanced disease or evidence of metastases." (PMID 39028303, 2024). "MIF is a proinflammatory cytokine, that has been implicated in various malignancies, including melanoma, where it contributes to tumor progression and metastasis through its effects on cell proliferation, angiogenesis, and immune evasion." (PMID 39916959, 2024). "MIF, an inflammatory cytokine linked with pathogenesis in multiple cancer types, is essentially involved in angiogenesis, immunity, and melanoma cell line metastasis." (PMID 37231440, 2023). "MIF is associated with progressive disease in human melanomas and is a potential target for advanced stages." (PMID 38260202, 2023). "Prior studies in human glioblastoma and melanoma associate MIF with cancer stem cells show that intercellular communication through MIF-CD74 is immunosuppressive, and that blocking MIF-CD74 signaling increases tumor-associated M1 macrophages." (PMID 34021242, 2021). "As a result, the expression of CD74 and the loss of MIF only showed a favorable overall survival in stage IV melanoma patients (p = 0.0264)." (PMID 33327409, 2020). "MIF acts on different immune cells and is implicated in the regulation of many immune pathways in cancer, particularly in melanoma." (PMID 31013837, 2019). "Tumor associated macrophages (TAMs) and myeloid-derived suppressor cells (MDSCs) from MIF-deficient mice exhibit reduced immunosuppressive activities resulting in improved immune responses against melanoma." (PMID 27636991, 2016). "Through in vitro analyses, a mechanism in suggested where MIF expression is associated with activation of Akt signalling and promotion of melanoma proliferation and survival." (PMID 25168062, 2014). "Loss of MIF expression in MelCV and Me1007 melanoma cell lines resulted in significantly less colonies in both cell lines compared to controls." (PMID 25168062, 2014). "Higher levels of MIF mRNA were identified within isogenic variants of the human A375 melanoma selected for higher metastatic potential in nude mice." (PMID 25168062, 2014). "Analysis of -173 G/C genotype frequencies revealed that the high-expression C/C genotype was 2.6 times more frequent in patients compared with controls (P < 0.000077), suggesting that high genotypic MIF expression may confer risk for melanoma development." (PMID 41122966, 2025). "Prevalence of variant MIF promoter alleles in human melanoma." (PMID 41122966, 2025). "In addition, overexpressed CD74 was reported to interplay with MIF to promote the tumor growth in advanced melanoma patients, and its elevated expression was associated with the poorer patient survival." (PMID 38874510, 2024). "A study performed at the University of Texas on metastasis of melanoma patients with stage III disease indicated that the presence of MIF protein expression in tumors was associated with poor survival parameters in both overall survival and relapse-free survival." (PMID 31013837, 2019). "The causative role of MIF in cancer progression was initially linked to its increased expression by a variety of cancer cells, including prostate, colon, hepatocellular, lung, ovarian, in addition to melanoma, glioblastoma and neuroblastoma." (PMID 25050663, 2014).